NNMT (nicotinamide N-methyltransferase)
Diseases named in the same sentence as NNMT in open-access papers (continued):
Sharing a sentence is not in itself a finding about the gene and the disease.
cancer (continued). "The NNMT enzyme appears to have the capacity to control the methylation status of cancer cells." (PMID 38542354, 2024). "Understanding role of NNMT in tumors provides valuable insights into tumor biology and may contribute to the development of novel anti-cancer therapies." (PMID 38809277, 2024). "A variety of NNMT inhibitors have been developed to treat numerous cancers." (PMID 38920648, 2024). "However, overall, NNMT inhibition seems to have a variety of promising anti-cancer effects, including anti-proliferative, pro-apoptotic, and chemo- and radio-sensitizing effects." (PMID 38920648, 2024). "Further investigations into NNMT's role in cancer pathogenesis could potentially pave the way for groundbreaking advancements in cancer treatment." (PMID 38809277, 2024). "This investigation may yield insights into role of NNMT in cancer progression and its implications for therapeutic strategies." (PMID 38809277, 2024). "NNMT downregulation enhances cancer cells’ sensitivity to these chemotherapeutics." (PMID 38396769, 2024). "The analysis of NNMT expression levels in different cancers from The Cancer Genome Atlas (TCGA) dataset indicates that NNMT might be a potential biomarker and therapeutic target in some cancers." (PMID 37834386, 2023). "In cancer, the expression of histone methyltransferases (HMTs) was inversely correlated to the activity of NNMT, an enzyme previously characterised as a methyl sink that disposes of excess methyl groups carried by the universal methyl donor S-adenosyl methionine (SAM or AdoMet)." (PMID 37883365, 2023). "Our findings reveal a novel molecular basis underlying EC’s high metastatic potential and raise the possibility that NNMT might be a future therapeutic target for this aggressive cancer." (PMID 37889548, 2023). "Interestingly, a recent report suggested that NNMT inhibits AMPK in a non-cancer disease in liver, where NNMT expression is higher in normal than cancer tissues." (PMID 36750850, 2023). "Interestingly, however, we observed that these changes were inversely correlated: cancers which up-regulate HMTs have reduced NNMT expression and vice versa." (PMID 37883365, 2023). "Additionally, a previous study found that NNMT is highly expressed in the matrix surrounding cancer cells and is considered a key regulatory molecule in maintaining fibroblast phenotype." (PMID 37953778, 2023). "Nicotinamide N-methyltransferase (NNMT) exerts a meaningful role in cancer progression." (PMID 38201930, 2023). "The importance of NNMT in cancer progression makes it an interesting therapeutic target." (PMID 37628772, 2023). "NNMT inhibitors hold promise as targeted therapies for cancer." (PMID 38067304, 2023). "Increased NNMT activity in cancer cells lowers histone methylation and SAM levels." (PMID 37834411, 2023). "In ccRCC, too, NNMT was suggested to be a cancer marker and contributor to metastasis." (PMID 36750850, 2023). "NNMT inhibitors are already available for targeting cancer and metabolic disorders." (PMID 37834411, 2023). "Therefore, it is particularly important to conduct an in-depth examination of the regulatory functions of NNMT in a pan-cancer dataset to provide new directions and strategies for the clinical treatment of cancer." (PMID 36817086, 2023). "Additionally, high stromal expression of NNMT—as a master metabolic regulator—has been correlated with poor prognosis in various types of human cancers." (PMID 37953778, 2023). "Cancer cells’ abnormal behaviour, such as maintaining proliferative signalling, evading growth suppressors, and resisting cell death, is essentially a product of NNMT’s control over methylation potential and energy metabolism." (PMID 37889548, 2023). "However, new investigations have revealed that the expression of NNMT is markedly elevated in a variety of cancers." (PMID 36386816, 2022). "Of note, NNMT transcription also showed a strong negative association with the expression of OXPHOS genes across these cancer cell lines." (PMID 36382559, 2022).
cancer (continued). "In addition, there was a link between NNMT expression and TMB and MSI in 18 cancer types, and between NNMT expression and DNA methylation in 23 cancer types." (PMID 36386816, 2022). "To check whether DNA methylation governed by DNMTs plays a role in the regulation of OXPHOS dependency for cancer cells, we examined cancer cell sensitivity to OXPHOS inhibition after manipulating the expressions of DNMT1 or NNMT or both." (PMID 36382559, 2022). "NNMT is a key regulatory element of cancer cell metabolism, especially the Warburg effect." (PMID 35756670, 2022). "Among human diseases in which NNMT seems to be involved, cancer displays a prominent role." (PMID 36139012, 2022). "Therefore, beyond its currently discussed role as a molecular diagnostic marker, NNMT represents a promising new target for the treatment of OSCC and potentially other cancer entities." (PMID 36291696, 2022). "The expression level of NNMT was detected from cancer tissues in 12 studies and serum in 1 study." (PMID 35233465, 2022). "Nicotinamide N-methyltransferase (NNMT) is highly expressed in a wide variety of cancers." (PMID 36120367, 2022). "Nicotinamide N-methyltransferase (NNMT) also modulates epigenetic events in cancer cells." (PMID 35935878, 2022). "For example, mutations in isocitrate dehydrogenase (IDH) and overexpression of nicotinamide N-methyltransferase (NNMT) enzymes occur in cancers, including HNSCC, promoting cancer progression and chemoresistance, and induce alterations in DNA and histone methylation profiles." (PMID 35408843, 2022). "In order to speculate NNMT involvement in mechanisms featuring chemosensitivity of ESCC cancer cell, three different cell lines (TE1, EC1, and Eca109) were first subjected to gas chromatography coupled with mass spectrometry (MS)." (PMID 36139012, 2022). "It is putative that NNMT may also be highly expressed in the stroma of PAAD and regulate gene expression patterns to facilitate the formation of a cancer-associated fibroblast phenotype." (PMID 35338115, 2022). "Based on these findings, NNMT overexpression in the stroma aids cancer prognosis prediction." (PMID 35756670, 2022). "Herein, we review the potential mechanism by which NNMT promotes cancer progression and resistance." (PMID 35756670, 2022). "Therefore, it is important to investigate the influence of NAM concentrations on NNMT-regulated chromatin modification in cancer cells." (PMID 35756670, 2022). "We then postulated that it might be the NNMT/DNMTs axis‐mediated DNA methylation that plays an important role in cancer cell sensitivity to OXPHOS inhibition." (PMID 36382559, 2022). "The overexpression of NNMT has been found in diverse human cancers." (PMID 35276059, 2022). "Taken together, NNMT might have miscellaneous effects on cancer cell metabolism that act together to support tumourigenesis and invasive cancer growth." (PMID 35678045, 2022). "Previous studies have revealed that NNMT expression increases considerably in cancer tissues." (PMID 35884600, 2022). "Previous studies had verified the important role of NNMT in cancer progression." (PMID 36313638, 2022). "Lastly, we introduce recent findings on NNMT inhibitors and their application in cancer therapy." (PMID 35756670, 2022). "NNMT in malignant tumors plays a pivotal role in cell proliferation, migration, and metastasis; its overexpression is consequently correlated with poor prognosis in several cancers." (PMID 35387964, 2022). "Moreover, by consuming SAM and generating a methylation sink within cells, NNMT inhibits the activities of other methyltransferases, leading to decreased histone and DNA methylation and consequently altered gene expression in cancer cells." (PMID 35678045, 2022). "When overexpressed, NNMT impairs the methylation balance of cancer cells by consuming methyl units, changes protein and gene methylation landscapes, and may result in hypomethylated histone and alteration of the epigenetic state of cancer cells." (PMID 35177765, 2022).
cancer (continued). "Combining NNMT and these regulators is likely to improve cancer prognosis." (PMID 35756670, 2022). "Therefore, beyond its currently discussed role as a drug target in metabolic conditions, NNMT represents a promising new target for the treatment of ccRCC and potentially other cancer entities." (PMID 35678045, 2022). "In late-stage cancers, NNMT mRNA expression also appeared to be increased in BRAF mutated cancers relative to BRAF wild type, although the difference was not statistically significant." (PMID 35177765, 2022). "An extremely low expression of NNMT in OXPHOS inhibition‐sensitive cancer cells implies this gene might be epigenetically silenced." (PMID 36382559, 2022). "The upregulation of NNMT may be related to the proliferation of various cancer cells, including esophageal squamous cell carcinoma, prostate cancer, neuroblastoma, lung cancer, gastric cancer, ovarian cancer, and breast cancer." (PMID 35851575, 2022). "Previous studies have indicated that NNMT expression is elevated in the stroma of many cancers." (PMID 35756670, 2022). "DNMT1 inhibition and NNMT activation render OXPHOS‐sensitive cancer cells resistant in vitro; we thus further examined the effects of S‐Gboxin and Berberine on tumor xenografts by NCI‐H82 cancer cells with NNMT overexpression and DNMT1 knockdown (NCI‐H82‐OE‐NNMT/sh‐DNMT1)." (PMID 36382559, 2022). "Accordingly, NNMT involvement in stromal cell and cancer cell interaction in the mechanical microenvironment may be a reason for the tumor metastasis." (PMID 35756670, 2022). "Finally, Nicotinamide N-Methyltransferase (NNMT) has been found to protect cancer cells from radiation." (PMID 33692493, 2021). "Knockdown of NNMT in CAFs, on the contrary, attenuated cancer cell proliferation and chemotaxis." (PMID 34073600, 2021). "In total, 21 different cancers have a somatic SNP in the NNMT gene; however, only 102 SNPs are represented in a combined 119 instances of cancer, thus it is impossible to determine whether SNPs are causative or coincidental." (PMID 34680055, 2021). "Once again, targeting NNMT could represent a powerful molecular strategy to effectively treat cancer." (PMID 34439880, 2021). "Interestingly, NNMT upregulation has been correlated with enhanced cancer cell migration and invasion, promoting the epithelial-mesenchymal transition (EMT), and with adverse clinical outcomes." (PMID 34827592, 2021). "Most studies on NNMT focus on its role in the pathology of cancer where elevated NNMT activity has been correlated with tumor aggressiveness and is proposed to promote migration, invasion, and proliferation, leading to its potential as a biomarker predictive of worsened clinical outcomes." (PMID 34572571, 2021). "In fact, NNMT overexpression has been reported for many solid tumors, including gastrointestinal neoplasms, lung, oral, esophageal, nasopharyngeal and thyroid cancers, as well as ameloblastoma and glioblastoma multiforme." (PMID 34439880, 2021). "In this review, we introduce a new player in the evolution of the cancer phenotype—nicotinamide N-methyltransferase (NNMT)—and discuss the evidence which places NNMT in the centre of a web of pathways which promotes the metabolic and cellular changes observed in many cancer cells." (PMID 34680055, 2021). "Its upregulation has been described in many solid malignancies including HNT, although the biological effects of NNMT expression and activity in cancer cell metabolism remains unclear." (PMID 34827592, 2021). "Several studies that investigated the activity and the biological role of NNMT, found high NNMT mRNA and protein levels and high catalytic activity in different cancer cell lines, including LSCC cell lines, ESCC cell lines EC9706 and TE1, and PTC cell line BHP 2-7." (PMID 34827592, 2021). "NNMT is overexpressed in various cancers and is related to proliferation, invasion, and metastasis." (PMID 35222522, 2021).
cancer (continued). "Thus, functional confirmation of the presence of these regulatory sites in the NNMT protein sequence will provide further insight into the promotion of the cancer phenotype by NNMT." (PMID 34680055, 2021). "The previous studies consistently reported that 1-MNA could be secreted into extracellular space and detected in plasma and somehow substitute the biological function of NNMT in cancers 41-43." (PMID 34539890, 2021). "On the contrary, NNMT overexpression in NPC and ESCC is associated with higher tumor size, advanced pathological staging, and the presence of lymph node metastasis, suggesting a role in cancer cell migration and invasiveness." (PMID 34827592, 2021). "Recently, NNMT has also been demonstrated to a master metabolic regulator of in several cancers and may be a therapeutically targeted." (PMID 33446144, 2021). "Notably, numerous cancer types and stromal cells upregulate NNMT expression, which epigenetically reprograms gene expression and causes a state of histone hypomethylation by consuming SAM methyl groups which, in turn, depletes SAM and creates a methyl sink." (PMID 34068917, 2021). "Moreover, the impact of NNMT expression in CAFs on tumor progression and metastasis was further supported by its overexpression in normal fibroblasts, which promoted cancer cell proliferation in vitro." (PMID 34073600, 2021). "Taken together, as NNMT, the enzyme that converts nicotinamide to MNAM, is overexpressed in a variety of human cancers, NNMT and metabolite productions are suggested to play a role in the malignant phenotype of cancer, including the involvement of the cancer stem cell phenotype." (PMID 34680237, 2021). "Epigenomic reprogramming is the main consequence of NNMT overexpression/activity in cancer." (PMID 34073600, 2021). "NNMT was discovered as a cancer-related protein in recent years." (PMID 32489327, 2020). "In the past decade, NNMT was found to be highly expressed in many kinds of tumour and was found to alter various cancer cell metabolism pathways to regulate the cellular stress response and epigenetic state, which results in high expression of pro-tumour genes." (PMID 32489327, 2020). "On the other hand, knockdown of NNMT suppresses cancer cell migration and EMT." (PMID 33182817, 2020). "Therefore, it is important to develop NNMT inhibitors to eradicate cancer propagation in the clinic." (PMID 36703437, 2020). "Although the functional role of NNMT in various cancers has been ascertained, the exact mechanism of its action is unknown." (PMID 31294922, 2019). "This study suggests that NNMT may promote cancer progression through desmoplasia and that NNMT overexpression in metastatic tissue is associated with poor survival." (PMID 31652035, 2019). "NNMT is overexpressed in many cancers and can result in an altered epigenetic state." (PMID 30672466, 2019). "However, NNMT expression has also been reported in a number of other types of cells and organs, including rapidly proliferating cancer cells or the brains of the patients suffering from Parkinson’s disease." (PMID 27412454, 2016). "Since suppression of NNMT inhibits proliferation of several types of human carcinoma cells, NNMT may become a possible molecular target for anti-cancer therapy." (PMID 27323852, 2016). "In this regard, the significant NNMT overexpression observed in tumors, leading to elevated intracellular levels of N1-methylnicotinamide, could confer an adaptive advantage to cancer cells." (PMID 23990942, 2013). "Moreover, downregulation of NNMT led to decreased KB cancer cell growth, suggesting the possibility of NNMT as a therapeutic target for the treatment of cancer." (PMID 23990942, 2013). "In addition, in nude mice NNMT downregulation induced a drastic reduction in tumor volume, suggesting the involvement of the enzyme in cancer development." (PMID 23990942, 2013).
cancer (continued). "NNMT activity affects proliferation of cancer cells, affects radiation sensitivity, and alters free radical production; nicotinamide affects genomic instability and cancer cells eat tryptophan." (PMID 22536229, 2012). "Given the association of NNMT with cancer aggressiveness, inhibiting its catalytic activity might present a novel strategy for counteracting cancer growth and chemoresistance, providing the rationale for an effective anti-cancer therapy based on the use of specific NNMT inhibitors." (PMID 41301471, 2025). "Furthermore, several NNMT inhibitors show promising results in targeting cancer." (PMID 38254784, 2024). "This is evidence that in RB1-mutant cancers, NNMT is not directly down-regulated by loss of Rb." (PMID 37883365, 2023). "Therefore, NNMT expression could serve as a promising prognostic factor and potential therapeutic target in various cancers, especially gastrointestinal cancer." (PMID 35233465, 2022). "Nicotinamide N-methyltransferase (NNMT) reduces the nicotinamide level inside the cell available for the energy metabolism by methylation, but at the same time hypomethylation of histones and other cancer-related proteins combined with heightened expression of pro-tumorigenic gene products occurs." (PMID 36012419, 2022). "Notably, NNMT inhibition might not only inhibit cancer cells themselves but also impact the activation status of tumour‐infiltrating T cells through its reaction product 1‐MNA." (PMID 35678045, 2022). "However, the bulk of scientific literature on NNMT is greatly focused on speculating and clarifying the role played by the enzyme in cancer." (PMID 34439880, 2021). "The analysis of NNMT expression levels in ccRCC demonstrated that the amount of upregulated enzyme is inversely correlated with tumor size, suggesting that the enzyme could play a role in cancer progression." (PMID 34638427, 2021). "Systematic exploration of NAM and its metabolites MNAM, 2PY, and 4PY in cancer, related to the expression of not only NNMT, but also NAMPT (the rate-limiting enzyme in NAD+ salvage pathway) and AOX1 (oxidizes MNAM to 2-PY and 4-PY), may provide a better insight into their function." (PMID 34073600, 2021). "Interestingly, NNMT overexpression also emerged in peripheral body fluids, such as blood and urine, thus leading to candidate the enzyme as promising biomarker for the early and non-invasive detection of these cancers." (PMID 34439880, 2021). "Moreover, this enzyme could be a promising target for cancer therapy, which can be studied in more detail thanks to the development of specific NNMT inhibitors which have shown promising results in preclinical studies." (PMID 34827592, 2021). "Therefore, NNMT overexpression could be related to tumor cell migration and cancer invasiveness in high-stage NPCs, and an aberrant activation of the pAkt pathway may contribute to tumoral progression." (PMID 34827592, 2021). "We discuss the regulation of NNMT activity in cancer cells by both post-translational modification of the enzyme and transcription factor binding to the NNMT gene, and describe for the first time three long non-coding RNAs which may play a role in the regulation of NNMT transcription." (PMID 34680055, 2021). "Generally, NNMT activity or expression is significantly elevated in cancers, such as brain, lung, liver, kidney, bladder, stomach, pancreas, colon, and oral cancer but cancer cells usually have a significantly higher anaerobic metabolism rate than normal cells." (PMID 34368359, 2021). "NNMT’s role in cancer progression could make it a target of EC therapy." (PMID 31652035, 2019). "Specifically, the cooperative action of NNMT and DNMT1 can lead to resistance in cancer cells to oxidative phosphorylation inhibitors, such as Gboxin." (PMID 40427612, 2025). "Nicotinamide N-methyltransferase (NNMT), a metabolic enzyme central to NAD+ and methionine cycles, has emerged as a critical regulator of tumorigenesis across cancers." (PMID 40427612, 2025).